KDM1A (lysine demethylase 1A)
Diseases named in the same sentence as KDM1A in open-access papers (continued):
Sharing a sentence is not in itself a finding about the gene and the disease.
bladder cancer (30 papers, 2011 to 2025). "Subsequently, we found that LINC00478 diminished the MMP9 expression via KDM1A recruitment in bladder cancer." (PMID 35504875, 2022). "Furthermore, LINC00478 is capable of suppressing the progression of bladder cancer through down-regulation of MMP9 by interacting with KDM1A." (PMID 35504875, 2022). "In lieu of the preceding evidence, we speculated the involvement of LINC00478 in bladder cancer progression via the mediation of KDM1A-dependent MMP9 demethylation." (PMID 35504875, 2022). "KDM1A exerts anti-cancer effect in bladder cancer through demethylating MMP940." (PMID 36357457, 2022). "Furthermore, KDM1A was shown to be involved in bladder cancer, while the immunoreactivity of KDM1A was shown to be elevated in hepatocellular carcinoma." (PMID 29921310, 2018). "Collectively, our findings unraveled a LINC00478-mediated inhibitory mechanism in bladder cancer via the recruitment of histone demethylation transferase KDM1A to the MMP9 promoter region, which can provide potential implications for novel therapeutic targets against bladder cancer." (PMID 35504875, 2022).
hepatocellular carcinoma (29 papers, 2013 to 2026). A malignant tumor that arises from hepatocytes. "The research showed that high expression of KDM1A is associated with a poor prognosis in hepatocellular carcinoma patients, indicating its potential as a prognostic biomarker." (PMID 38965210, 2024). "We performed immunohistochemical staining and survival analysis of KDM1A using 90 hepatocellular carcinoma tissue samples and found that high expression of KDM1A indicated poor prognosis." (PMID 38965210, 2024). "KDM1A, commonly known as lysine-specific histone demethylase 1, has been reported to increase glucose uptake in hepatocellular carcinoma." (PMID 38295985, 2024). "Further analysis of RNA-seq data in hepatocellular carcinoma with KDM1A downregulation revealed significant enrichment of conserved motifs of HNF4A in the promoters of KDM1A-negative regulatory genes (HOMER: P = 1e−14, Rank 1)." (PMID 38965210, 2024). "KDM1A reinforces the immunosuppression in hepatocellular carcinoma through demethylating MEF2D and activating PD-L139." (PMID 36357457, 2022). "Moreover, we discover a signaling axis in which liver-TEs, KDM1A, and the liver-TE-associated gene (HNF4A) synergistically control the proliferation of hepatocellular carcinoma cells." (PMID 38965210, 2024). "Moreover, Liu and colleagues reported that upregulated KDM1A expression in CAFs is a driver of Notch3-mediated cancer stem-like cells self-renewal in hepatocellular carcinoma." (PMID 34925656, 2021). "Additionally, we analyzed the clinical correlations of KDM1A expression level, ZMYM3 expression level, liver-TE-related gene expression profiles, and HNF4A downstream gene expression profiles in the TCGA and ICGC hepatocellular carcinoma expression profile datasets." (PMID 38965210, 2024).
glioma (27 papers, 2013 to 2025). A benign or malignant brain and spinal cord tumor that arises from glial cells (astrocytes, oligodendrocytes, ependymal cells). "Inhibiting KDM1A has been shown to sensitize glioma stem cells (GSCs) to TMZ, indicating its involvement in TMZ resistance." (PMID 39239542, 2024). "HDAC-related genes upregulated in IDH1/2mut glioma include HDAC2/4/5, KDM1A, CHD4, MTA2/3, SIRT1/2, PHF21A, and BRMS1L." (PMID 34424450, 2021). "The phosphorylation of KDM1A Ser683, PGK1 T243, Atoh1 tyrosine 78, YTHDF2 Ser39, and Thr381 can promote tumorigenesis, and if we can effectively control the phosphorylation of these proteins, we can prevent the development of glioma." (PMID 37786890, 2022).
triple-negative breast carcinoma (25 papers, 2015 to 2025). An invasive breast carcinoma which is negative for expression of estrogen receptor (ER), progesterone receptor (PR), and human epidermal growth factor receptor 2 (HER2). "The main member of the amine-oxidase type lysine-specific demethylases, KDM1A (also known as LSD1), is a direct target of miR-708 in triple negative breast cancer." (PMID 31252590, 2019). "Furthermore, the expression levels of KDM1A and HDAC isozymes are correlated, i.e., KDM1A knockdown induces a decrease in the expression of HDAC5 in triple-negative breast cancer, while the depletion of HDAC5 leads to the accumulation of H3K4me2." (PMID 29921310, 2018).
liver cancer (23 papers, 2013 to 2025). An epithelial or non-epithelial malignant neoplasm that arises from the liver. "This provides mechanistic insight into the inherent connection between KDM1A and liver-TE-associated gene expression in liver cancer." (PMID 38965210, 2024). "Our results demonstrated a diminished binding capability of KDM1A to these TEs in normal liver cells compared to HCC cells, suggesting potential aberrant recruitment of KDM1A to liver-specific TEs within liver cancer cells." (PMID 38965210, 2024). "Subcutaneous tumorigenicity assays in nude mice demonstrated that KDM1A knockdown significantly inhibited the in vivo tumorigenicity of liver cancer cells." (PMID 38965210, 2024). "In liver cancer, KDM1A promotes cancer growth and drug resistance by regulating signals such as FKBP8/Bcl2 or LINC01134/SP1/p6221–24." (PMID 38965210, 2024). "By using an IP-LC-MS approach, we identified eight DNA-binding proteins that are present in KDM1A immunoprecipitants in liver cancer cells." (PMID 38965210, 2024). "In conclusion, this study uncovers a liver-TE/KDM1A/HNF4A regulatory axis that promotes liver cancer growth and highlights KDM1A as a promising therapeutic target." (PMID 38965210, 2024). "Our study emphasizes the critical role of KDM1A in regulating liver cancer cell growth through two mechanisms involving HNF4A." (PMID 38965210, 2024). "Our findings strongly suggest that ZMYM3 is necessary for the epigenetic regulatory role of KDM1A and is vital for KDM1A to exert its pro-growth effect in liver cancer cells." (PMID 38965210, 2024). "The liver-TE/KDM1A/HNF4A regulatory loop exemplifies the intricate interplay between these factors in liver cancer development and progression." (PMID 38965210, 2024). "We found that the restrained in vitro and in vivo cell growth caused by KDM1A knockdown was partially restored by HNF4A downregulation, indicating that KDM1A promotes the growth of liver cancer cells by inhibiting the expression of HNF4A." (PMID 38965210, 2024). "To assess the relative importance of KDM1A in liver cancer cell growth compared to other histone methylation regulators, we ranked their mean dependency scores derived from RNAi screen results in the DepMap database." (PMID 38965210, 2024). "Our findings shed light on the regulatory mechanisms of liver cancer growth by KDM1A and HNF4A, highlighting their essential roles in liver-TE accessibility and transcriptional activity." (PMID 38965210, 2024). "Knockdown of KDM1A significantly inhibited liver cancer cell growth both in vitro and in vivo, highlighting the essential role of KDM1A in HCC cell growth." (PMID 38965210, 2024). "Functionally, we found that knocking down ZMYM3 inhibits KDM1A-mediated growth of liver cancer cells." (PMID 38965210, 2024). "Colony formation assays demonstrated significant inhibition of liver cancer cell growth upon KDM1A downregulation, while KDM1A overexpression promoted cell growth." (PMID 38965210, 2024). "Functionally, we reveal that FKBP8 demethylation by KDM1A is critical for liver cancer cell growth in vitro and in vivo." (PMID 35970393, 2022). "To ascertain whether the promoting effect of KDM1A on liver cancer depends on its regulation of HNF4A, we simultaneously silenced KDM1A and HNF4A in liver cancer cells." (PMID 38965210, 2024). "To identify liver cancer suppressor genes related to liver-TE that are controlled by KDM1A-mediated HNF4A repression, we focused on MAT1A, a known HNF4A target gene associated with liver-TE which is directly repressed by KDM1A." (PMID 38965210, 2024). "The suppression of HNF4A mediated by KDM1A promotes liver cancer cell proliferation." (PMID 38965210, 2024). "Furthermore, pharmacological inhibiting KDM1A with small-molecule inhibitors dramatically attenuating liver cancer cell growth." (PMID 38965210, 2024). "Functionally, knocking down ZMYM3 inhibits KDM1A-mediated growth of liver cancer cells." (PMID 38965210, 2024).
liver cancer (continued). "To test this hypothesis, we conducted Co-IP experiments and confirmed that endogenous KDM1A interacts with HNF4A in liver cancer cells." (PMID 38965210, 2024). "The results indicated a high dependency of liver cancer cells on KDM1A." (PMID 38965210, 2024). "Furthermore, our findings highlight the critical function of KDM1A in the growth of liver cancer cells through liver-TE-mediated mechanisms, specifically by repressing the transcriptional activity of HNF4A." (PMID 38965210, 2024). "Additionally, the use of a small-molecule inhibitor targeting KDM1A substantially suppressed the growth of liver cancer cells, indicating KDM1A as a promising target for HCC treatment." (PMID 38965210, 2024). "To examine the role of KDM1A in HCC cell growth, we knocked down KDM1A in HLF human liver cancer cells and detected significant decrease in cell proliferation, which could be ameliorated by expressing exogenous KDM1A." (PMID 35970393, 2022). "This suggests that KDM1A downregulates the activity of the HNF4A-regulated hepatocyte-specific methionine metabolic pathway, ultimately promoting liver cancer." (PMID 38965210, 2024). "Consistently, we observed positive correlation between KDM1A and BCL2 protein levels in liver cancer patients." (PMID 35970393, 2022). "Similarly, the application of SP2509, a KDM1A inhibitor, heightened HNF4A expression in liver cancer cells." (PMID 38965210, 2024). "Moreover, highly expressed KDM1A was coupled with poor OS, RFS, PFS, and DSS (all p < 0.001) for the cases of liver cancer." (PMID 34925656, 2021).
viral infection (18 papers, 2016 to 2024). "KDM1A forms a part of protein complexes that regulate the expression of genes involved in the onset and progression of diseases such as cancer, central nervous system (CNS) disorders, viral infections, and others." (PMID 35890315, 2022). "Furthermore, KDM1A downregulates PD-1 expression of CD8 T cells via histone H3K4 modification following acute viral infection." (PMID 34925656, 2021).
medulloblastoma (17 papers, 2013 to 2026). A malignant, invasive embryonal neoplasm arising from the cerebellum. "In the case of medulloblastoma, one can observe an overexpression of histone demethylase KDM1A, which causes the demethylation of lysine 4 in histone 3 (H3K4), which is connected with a poor prognosis." (PMID 34066495, 2021). "We further used cell models for medulloblastoma to assess the role of KDM1A in processes associated with malignancy, including the regulation of cell proliferation, death and motility." (PMID 24252778, 2013). "The treatment of medulloblastoma cells with a novel specific LSD1/KDM1A inhibitor, the small molecule NCL-1, led to the significant inhibition of cellular growth in vitro." (PMID 38612726, 2024). "Here we show that medulloblastomas driven by the transcription factor Gfi1 are exquisitely dependent on the enzyme lysine demethylase 1 (Kdm1a/Lsd1)." (PMID 30659187, 2019). "The DAOY and ONS-76 medulloblastoma cell lines were transiently transfected with siRNA directed against KDM1A or with transfection agent alone." (PMID 24252778, 2013). "Taken together, our data from cellular models for medulloblastoma show that KDM1A influences three major hallmarks of cancer cells, uncontrolled cell proliferation, avoidance of apoptosis and migratory capacity." (PMID 24252778, 2013). "As a first step to analyze the role of KDM1A in medulloblastoma, we assessed KDM1A expression in 62 primary human medulloblastomas." (PMID 24252778, 2013). "We next investigated KDM1A expression in a panel of cell lines derived from medulloblastomas using real-time RT-PCR." (PMID 24252778, 2013). "KDM1A inhibition can effectively antagonize important hallmarks of medulloblastoma progression including proliferation, resistance to apoptosis and migration." (PMID 24252778, 2013). "Re-analysis of publicly available microarray data revealed a highly significant upregulation of KDM1A mRNA in primary medulloblastomas compared to normal human cerebellum." (PMID 24252778, 2013). "Treatment of medulloblastoma cells with a novel specific KDM1A inhibitor, the small molecule NCL-1, led to significant inhibition of cellular growth in vitro." (PMID 24252778, 2013). "Since our data indicated that KDM1A is highly relevant for critical biological characteristics of medulloblastoma, we next aimed to identify important target genes of KDM1A." (PMID 24252778, 2013). "These experiments show that KDM1A knockdown impaired medulloblastoma cell viability and proliferation and induced apoptosis." (PMID 24252778, 2013). "We provide the first evidence that a histone demethylase is functionally involved in the regulation of the malignant phenotype of medulloblastoma cells, and lay a foundation for future evaluation of KDM1A-inihibiting therapies in combating medulloblastoma." (PMID 24252778, 2013). "In conclusion, data resulting from our work lay a first preclinical foundation for future evaluation of KDM1A-inhibiting therapeutic approaches against medulloblastoma including transgenic and xenograft mouse models." (PMID 24252778, 2013). "Re-analysis of gene expression data and immunohistochemistry of tissue microarrays of human medulloblastomas showed strong KDM1A overexpression in the majority of tumors throughout all molecular subgroups." (PMID 24252778, 2013). "Medulloblastomas, cell lines derived from medulloblastomas and meduloblastic tumors from genetically engineered mouse models for medulloblastoma exhibit high-level KDM1A expression in comparison to normal cerebellar tissue." (PMID 24252778, 2013). "Taken together, these data show extensive KDM1A deregulation in primary human medulloblastoma, cell lines derived from them and murine medulloblastic tumors, suggesting a crucial role for KDM1A in medulloblastic tumors across species." (PMID 24252778, 2013).
medulloblastoma (continued). "This is in line with our findings in the current study, showing that approximately 90% of primary human medulloblastomas that predominantly consist of cells with undifferentiated appearance, were shown to be KDM1A positive." (PMID 24252778, 2013). "Here, we show that the migratory activity of medulloblastoma cells was significantly reduced by KDM1A knockdown." (PMID 24252778, 2013). "In this study, we analyzed KDM1A expression in primary human medulloblastomas and murine medulloblastic tumors." (PMID 24252778, 2013). "Based on our data demonstrating that apoptosis is induced even in DAOY cells following KDM1A knockdown, we suggest that KDM1A inhibition can circumvent the blockade of BMP2-mediated apoptosis in medulloblastoma cells incapable of responding to retinoids." (PMID 24252778, 2013). "Treating medulloblastoma cells with the specific KDM1A inhibitor, NCL-1, significantly inhibited growth in vitro." (PMID 24252778, 2013). "Taken together, these findings suggest a role of KDM1A in the motility and invasiveness of cancer cells of various origins including medulloblastoma, which might be based on induction of mesenchymal cellular properties." (PMID 24252778, 2013). "We suggest that BMP2 upregulation in response to KDM1A knockdown could be an intermediate to inducing apoptosis in medulloblastoma cells, but acting via routes different from sonic hedgehog pathway inhibition." (PMID 24252778, 2013). "Finally, we tested the efficacy of a novel small molecule inhibitor of KDM1A in cell models for medulloblastoma." (PMID 24252778, 2013). "Since it is critical for therapy success that the treatment kills tumor cells, and not just arrests them during the cell cycle, we next assessed whether KDM1A knockdown induced apoptosis in medulloblastoma cells." (PMID 24252778, 2013). "To investigate whether KDM1A can also influence migratory capacity in medulloblastoma cells, we used Boyden chamber assays to assess migratory capacity after KDM1A knockdown." (PMID 24252778, 2013). "We show here that BMP2 was upregulated in medulloblastoma cell lines following KDM1A knockdown." (PMID 24252778, 2013). "Interestingly, KDM1A knockdown in medulloblastoma cell lines not only induced apoptosis and suppressed proliferation, but also impaired migratory capacity." (PMID 24252778, 2013). "We next examined whether KDM1A knockdown had a notable impact on tumorigenic characteristics in medulloblastoma cells." (PMID 24252778, 2013). "The targeting of KDM1A in this tumor may lay the foundation for effective medulloblastoma therapy." (PMID 29921310, 2018). "Specific inhibition of KDM1A, for instance via the NCL-1 small molecule inhibitor, presents a promising new strategy to treat medulloblastoma, which should be clinically evaluated." (PMID 24252778, 2013). "KDM1A knockdown effectively diminished the strong migratory capacity of both DAOY and ONS-76 medulloblastoma cells." (PMID 24252778, 2013). "Interestingly, re-analysis of KDM1A expression in distinct medulloblastoma subtypes did not reveal significant differences between KDM1A expression levels in the subgroups." (PMID 24252778, 2013). "However, the most commonly used medulloblastoma-derived cell lines, which we also used here, are not depending on constitutive activation of sonic hedgehog signaling and KDM1A knockdown did not result in any significant change of expression in genes belonging to the sonic hedgehog signaling pathway." (PMID 24252778, 2013).
breast tumor (16 papers, 2012 to 2025). "H3K4 demethylation by KDM1A affects the expression of the p57Kip2 gene, which encodes a cyclin-dependent kinase inhibitor that is essential for breast tumor development." (PMID 29921310, 2018). "KDM1A expression is also required for the proper functioning of ERα, which is highly expressed in the majority of breast tumors." (PMID 29921310, 2018).